ARID1A (AT-rich interaction domain 1A)
Diseases named in the same sentence as ARID1A in open-access papers (continued):
Sharing a sentence is not in itself a finding about the gene and the disease.
cancer (continued). "By far, several therapeutic targets with the potential of specifically targeting ARID1A-mutated cancers have been revealed." (PMID 34671561, 2021). "Up to now, several studies have revealed the synthetic lethal targets with ARID1A deficiency as a potential strategy for cancer treatment." (PMID 34671561, 2021). "ARID1A loss in cancer cells leads to increased cell proliferation, migration, and invasion, as well as reduced cell apoptosis and chemosensitivity." (PMID 34671561, 2021). "ARID1A is one of the few genes that are mutated in pre-existing genomically unstable cancer cells, and the importance of ARID1A mutations is underestimated." (PMID 34804958, 2021). "ARID1A-deficient cancer cells are specifically vulnerable to inhibitors of the antioxidant glutathione metabolic pathway and the glutamate–cysteine ligase synthetase catalytic subunit, a rate-limiting enzyme for glutathione synthesis." (PMID 34067626, 2021). "AT-rich interaction domain 1A (ARID1A) loss in premalignant EH is an accurate and almost perfectly specific prognostic marker for coexistent cancer." (PMID 34433451, 2021). "Loss of ARID1A expression (lost ARID1A) has been observed in cancers of the ovary, endometrium, and colon, and mutation of the ARID1A gene is closely associated with the loss of protein expression." (PMID 34469459, 2021). "Other members of the SWI/SNF complex, most notably ARID1A/B, are among the most frequently mutated targets in all human cancers." (PMID 33404859, 2021). "Indirect or adaptive changes dominate the transcriptome following growth for days after loss of ARID1A and result in strong engagement with cancer pathways." (PMID 34731603, 2021). "Reduced ARID1A mRNA expression has been associated with poor prognosis in several cancers, and with decreased intracellular glutathione (GSH) level, which in turn increases production of reactive oxygen species and DNA damage." (PMID 34042280, 2021). "Clinical trials of the PARP inhibitors olaparib and niraparib, using ARID1A deficiency as a biomarker, are underway in ovarian and other cancers (NCT04065269, NCT04042831, NCT03207347)." (PMID 33917230, 2021). "Dysfunction of the SWI/SNF complex due to ARID1A-deficiency leads to predominance of PRC2 activity in cancer cells." (PMID 33917230, 2021). "In the entire cohort, ARID1A mutated carcinomas are prevalently endometrioid, undifferentiated/dedifferentiated and exhibit histopathologic features such as MELF, presence of TILs and high proliferative index." (PMID 33668727, 2021). "Several reports have demonstrated association between loss of ARID1A protein expression and cancer progression in various cancer." (PMID 33344089, 2020). "EZH2 inhibition in ARID1A mutated tumors acts in a synthetically lethal manner to inhibit cancer progression, revealing a therapeutic opportunity." (PMID 33344089, 2020). "It has been noted that mutations and deficiencies in ARID1A have been shown to sensitize cancers to PARP and PI3K inhibitors." (PMID 32175276, 2020). "Loss of ARID1A function is a common driver of ovarian and some other cancer types, and it confers vulnerability to inhibition of GSH." (PMID 31940398, 2020).
cancer (continued). "Recent studies also reported that inhibition of enhancer of zeste homolog 2 (EZH2), the catalytic subunit of PRC2, caused synthetic lethality in ARID1A‐mutated cancers." (PMID 32162380, 2020). "COSMIC data demonstrated that more than half of ARID1A mutations are loss-of-function mutations, including frameshift indels mutations, and nonsense mutations, that lead to a loss of ARID1A protein expression in cancer cells." (PMID 32868822, 2020). "Taken together, these results suggest that the two-hit would be necessary for benign endometriosis with ARID1A heterozygous mutation to transform into malignant tumor." (PMID 32868822, 2020). "Preclinical data also demonstrated that ARID1A mutation sensitizes anti-PDL1 in several types of cancer." (PMID 33409155, 2020). "Through systematic analyses of the datasets from the cBioPortal for Cancer Genomics, we found that both ARID1A and ARID1B mutations were associated with an improved outcome for ICIs treatment in advanced NSCLC patients." (PMID 32791957, 2020). "Current bioinformatic analysis has revealed that ARID1A encodes an SWI/SNF chromatin-remodeling factor that is frequently mutated in a variety of cancers." (PMID 32978257, 2020). "Mutations to the C-terminus of ARID1A (including Y2254), which acts as the core of the Body module, are common in cancer and would be expected to have equally deleterious effects on complex stability." (PMID 32629987, 2020). "The role of ARID1A as a scaffold for BAF complex assembly is especially pertinent as there is a high occurrence of inactivating frameshift mutations in ARID1A in cancer." (PMID 32629987, 2020). "Loss of ARID1A expression was found to increase the response of cancer cells to PI3K and AKT inhibitors significantly." (PMID 31906887, 2020). "Loss-of-function ARID1A mutations sensitized various cancer cells towards inhibition of EZH2, PARP, ATR, HSP90 and HDAC9 (and others)." (PMID 32272809, 2020). "ARID1A loss-of-function mutations sensitize cancer cells towards inhibition of EZH2, ATR, PARP, HDAC6, and HSP90 (and others)." (PMID 32272809, 2020). "SLC7A11 expression is lower in ARID1A-deficient compared with ARID1A-proficient cancer cells, contributing to a decrease in basal GSH levels and an increase in ROS in ARID1A-deficient cells." (PMID 32978257, 2020). "Previous studies have revealed the relevance of ARID1A mutation or protein loss to survival in several carcinomas, although the findings were varied." (PMID 33344089, 2020). "ARID1A is frequently mutated in a wide variety of cancers and its mutation is associated with a poor prognosis in certain cancers such as liver cancer and breast cancer." (PMID 31277418, 2019). "ARID1A increases the risk for cancer by promoting CYP450 (CYP2E1) transcriptional activation and reactive oxygen species (ROS) production in vivo, while decreasing metastasis via the transcriptional regulation of EMILIN1/MAT1A/LCN2/IL1R1 in vitro." (PMID 31238554, 2019). "Insufficient DNA damage response in ARID1A-deficient cancer cells is likely to further increase oxidative stress induced DSBs, ultimately leading to cell death." (PMID 31426306, 2019). "HDAC6 was observed to function as a promising therapeutic target for OCCC with ARID1A loss, in close association with immuno-modulation, response to hypoxia, and cancer stem cell phenotype." (PMID 30787326, 2019). "Our results demonstrate a novel approach to selectively increase radiation sensitivity in ARID1A-mutated cancers." (PMID 31796878, 2019). "In the Allen and Hugo cohorts, ARID1A-mutated cancers had favorable OS trends compared to ARID1A-wildtype cancers (log-rank test, P = 0.095 and 0.333 for Allen and Hugo cohorts, respectively)." (PMID 31277418, 2019). "Compared with ARID1A wild-type tumors, ARID1A-mutated tumors display significantly less CNAs across multiple cancer types." (PMID 31492885, 2019).
cancer (continued). "These functions of ARID1A would predict large-scale genomic alterations and aneuploidy in ARID1A-mutated cancers caused by mitotic defects." (PMID 31492885, 2019). "Paradoxically, cancers with high ARID1A mutation rates typically lack copy number alterations (CNAs)." (PMID 31492885, 2019). "By using NGS technologies, somatic mutations in several novel cancer-related genes such as ARID1A (7.53%), HNF4α (0.88%), FAT4 (4.71%) and IRF2 (1.06%) have been identified and suggested to be associated with HCC." (PMID 31395065, 2019). "The loss of ARID1A been observed in several types of human cancers and associated with poor patient prognosis." (PMID 31210753, 2019). "Several potential targets selective against ARID1A mutation in cancers have been proposed based on the context of the cellular signaling in the respective organ-type cancers." (PMID 31731647, 2019). "Of the acquired mutations (range: 1–7 mutations) in 9 cancer genes, the mutation frequencies of ARID1A (50%) and BRCA2 (50%) were the highest." (PMID 31592412, 2019). "Paradoxically, cancer types associated with high frequency of ARID1A mutations typically lack widespread genomic instability as measured by copy number alterations (CNA)." (PMID 31492885, 2019). "Following the discovery of frequent inactivating alterations of ARID1A, several approaches to therapeutically target ARID1A-deficient cancer cells have been proposed." (PMID 30858552, 2019). "Among BAF complex subunits, ARID1A mutations are the most recurrent and widespread across many cancer types." (PMID 31217031, 2019). "Several other cancer driver genes, such as ARID1A, FAT4, and PIK3CA, were also found to mutated in more than 10% of GC samples." (PMID 31781598, 2019). "In the Samstein cohort (pan-cancer), ARID1A-mutated cancers had a significantly better OS than ARID1A-wildtype cancers (log-rank test, P = 0.005)." (PMID 31277418, 2019). "Similar to the vulnerability to GSH inhibitors discovered in ARID1A-deficient cancer cells, the iron exporter ferroportin (FPN) has been observed to be dysregulated in tumor cells." (PMID 31434226, 2019). "Sequencing of cancer genomes has identified recurrent mutations of ARID1A in a wide range of tumors including gynecological, liver, gastric, and breast tumors." (PMID 30858552, 2019). "Mutations in other conventional drivers (APC, KRAS, PIK3CA, ARID1A) were usually clonal within a carcinoma." (PMID 29991641, 2019). "ARID1A and ARID1B are typically co-expressed in cancer, but cancer driven by ARID1A mutation retains at least one functional ARID1B allele." (PMID 29890703, 2018). "They suggest BCL2 inhibition alone or in combination with EZH2 inhibition represents urgently needed therapeutic strategy for ARID1A-mutated cancers." (PMID 30297712, 2018). "The selective induction of apoptosis in ARID1A-deficient cancer was further confirmed in the ARID1A isogenic RKO xenograft mouse model." (PMID 30097580, 2018). "This interaction was observed across 496 cancer cell lines where ARID1A expression was strongly linked with etoposide sensitivity (r = −0.297, p = 1.5e–11) and low ARID1A expression was highly predictive of resistance to etoposide (94.8% precision)." (PMID 29669295, 2018). "Interesting results were found in a recent study on ARID1A, the third most significantly mutated gene in human colorectal cancers, with the highest frequency (39%) in cancers of the MSI-H type." (PMID 29652830, 2018). "Since the discovery of the high frequency of mutations and loss of expression of ARID1A in cancer, ARID1A deficiency has been exploited therapeutically for treating cancer according to an approach called synthetic lethality." (PMID 30097580, 2018). "As ARID1A mutations are detected in endometrioma, it has been suggested that they are involved in the onset and progression of cancer." (PMID 29599905, 2018).
cancer (continued). "The Cancer Genome Atlas further confirmed that ARID1A is mutated in a high proportion of type I uterine cancers, particularly in the POLE hypermutated, microsatellite unstable (MSI) hypermutated, and copy-number low subgroups." (PMID 29093822, 2017). "While it is unclear if ARID1A mutations alone are sufficient to induce cancer progression, concurrent mutations in alternate pathways, including the PI3K/AKT pathway are frequent and appear to occur simultaneously to facilitate tumorigenesis." (PMID 29093822, 2017). "ARID1B is synthetic lethal with ARID1A mutation in cancer cell lines and fibroblasts, consistent with the presence of intact ARID1B-containing complexes." (PMID 28967863, 2017). "Several therapeutic targets in ARID1A mutated cancers are in development, including EZH2 inhibitors." (PMID 29093822, 2017). "Samartzis and co-investigators reported that PI3K/AKT-pathway activation is also a crucial mechanism in ARID1A-mutated cancers and, consequently, ARID1A-deficient tumors show preclinical sensitivity to treatment with PI3K/Akt/mTor pathway inhibitors." (PMID 28854942, 2017). "A total of 409 genes from the Ampliseq Comprehensive Cancer Panel (Ion Torrent, Thermo Fisher) were analysed by next generation sequencing and mutations in 10 genes, including ARID1A, CTNNB1, PIK3CA and PTEN were identified and confirmed by Sanger sequencing." (PMID 28103826, 2017). "The absence of SWI/SNF complexes dysregulates these processes, resulting in altered expression of key genes in cancer pathways, consistent with reduced cancer cell growth observed upon loss of ARID1A and ARID1B." (PMID 28967863, 2017). "This review will synthesize the molecular carcinogenesis of these malignancies and their unique clinical behavior, as a foundation for an emerging frontier of targeted therapeutics – the synergistic inhibition of EZH2 in ARID1A mutated cancers." (PMID 29093822, 2017). "First, we determined the ARID1A mutation statuses of all the cancer cell lines using the Cancer Cell Line Encyclopedia database." (PMID 27486766, 2016). "Other frequently mutated EAC driver genes included NOTCH1 (N=8 cancers), ARID1A (N=7), CNTNAP5 (N=3), PIK3CA (N=3) and SMARCA4 (N=3)." (PMID 27045317, 2016). "ARID1A mutations are also prevalent in cancers of other tissues, including subtypes of breast and gastric cancers (8, –10)." (PMID 27654507, 2016). "Mutations in ARID1A represent one of the most common molecular alterations in human cancer, but therapeutic approaches that target these defects are not yet clinically available." (PMID 27958275, 2016). "Although it has been demonstrated that ARID1A deficiency leads to sensitization to several inhibitors, therapeutic strategies that target ARID1A-mutant cancers remain limited." (PMID 27486766, 2016). "The tumor suppressor gene AT-rich interactive domain-containing protein 1A (ARID1A) was frequently mutated in cancers." (PMID 27323812, 2016). "Identification of the mevalonate pathway as the primary target of ARID1A loss of function suggests areas for further investigation and potential therapeutic targeting for ARID1A-mutated cancers." (PMID 27654507, 2016). "Mutation of ARID1A likely drives cancer progression by increasing dependence on alternative SWI/SNF complexes with partially overlapping transcriptional profiles." (PMID 27654507, 2016). "We first determined ARID1A mutation statuses in these cell lines using the Cancer Cell Line Encyclopedia database, DNA sequencing, and western blot analysis." (PMID 27486766, 2016). "Recently, certain genes encoding components of SWI/SNF complexes, in particular ARID1A, have been reported to be frequently mutated in a wide variety of human cancers." (PMID 26569409, 2015). "We aimed to investigate the risk associated with loss of ARID1A (ARID1A−) for all-cause mortality, cancer-specific mortality and recurrence of disease in subjects with cancer." (PMID 26384299, 2015).
cancer (continued). "A recent paper identified a synthetic lethal interaction between EZH2 and ARID1A in ARID1A-mutated cancers, thus providing therapeutic opportunities since EZH2 can be pharmacologically targeted." (PMID 26579514, 2015). "On the basis of these results, we have demonstrated that loss of ARID1A shortened time to cancer-specific mortality, and to recurrence of cancer when adjusting for potential confounders." (PMID 26384299, 2015). "Assessing the ARID1A mutational status in different types of cancers allows for a more differentiated risk evaluating." (PMID 26384299, 2015). "In conclusion, loss of ARID1A shortened time to cancer-specific mortality as well as to recurrence of disease when adjusting for potential confounders." (PMID 26384299, 2015). "A broad spectrum of cancers has been shown to carry mutations in ARID1A, particularly deletion or nonsense mutations that are distributed throughout the ARID1A gene." (PMID 26544626, 2015). "Usually, ARID1A mutation is an early event in neoplastic transformation and it is present both in carcinoma and preneoplastic tissue whilst HNF1B is usually found only in cancer tissue." (PMID 25885815, 2015). "The findings suggest a specific requirement of the PI3K/AKT pathway in ARID1A-deficient cancer cells and reveal a synthetic lethal interaction between loss of ARID1A expression and inhibition of the PI3K/AKT pathway." (PMID 24979463, 2014). "In conclusion, ARID1A-deficient cancer cells demonstrate an increased sensitivity to treatment with small molecule inhibitors of the PI3K/AKT-pathway." (PMID 24979463, 2014). "The AT-rich interactive-containing domain (ARID) gene superfamily consists of seven members (ARID1–5), of which the following have now been implicated in cancer: ARID1A/BAF250a, ARID1B/250b, and ARID2/BAF200." (PMID 24622842, 2014). "Exciting new evidence is emerging from the discovery that ARID1A-mutant cancer cells are highly vulnerable to loss of ARID1B expression, and similarly for BRG1/SMARCA4-mutated cancers to the loss of BRM/SMARCA2." (PMID 25927994, 2014). "Exploiting ARID1A deficiency has emerged as a therapeutic strategy in these types of cancer." (PMID 41800254, 2026). "ARID1A is mutated among ICI responders in several cancer types, including ccRCC." (PMID 41484569, 2026). "ARID1A mutations increase the sensitivity of these cancer cells to GCLC depletion, indicating that targeting GCLC could selectively attack cancer cells while sparing normal cells, thereby reducing the risk of excessive ROS buildup and DNA damage." (PMID 41333220, 2025). "Furthermore, ARID1A-deficient cancer cells also exhibit elevated type I IFN response signaling, promoting CD8+ T-cell recruitment and cytolytic activity." (PMID 40750787, 2025). "ARID1A is among the ten most commonly mutated genes in cancer." (PMID 39843653, 2025). "We hypothesized that the cancer immunogenicity of ARID1A-deficient cells was increased for dendritic cell recognition to attract infiltrating immune cells via the ssDNA/CHK1/cGAS/STING pathway." (PMID 40750787, 2025). "Additionally, ARID1A mutations have been linked to improved responses to ICIs in multiple cancer types." (PMID 40429787, 2025). "Additionally, immune exclusion, a cancer hallmark feature, is observed within ARID1A-deficient clones in histologically normal tissue." (PMID 39920335, 2025). "ARID1A mutations also occur in common cancers (e.g., colon, endometrial); thus, our findings in OCCC cells could have broader clinical significance." (PMID 40564930, 2025). "The ARID1A subunit of the BAF chromatin remodeling complex is frequently mutated in cancer." (PMID 40938753, 2025). "Overall, our work identifies KLF5 as a potential target for eradicating ARID1A-deficient cancers." (PMID 39779698, 2025). "The high frequency of ARID1A mutation in cancer highlights its importance in oncogenesis." (PMID 39796161, 2025). "Mutations in ARID1A are frequently observed in several types of cancer, including PDEECs." (PMID 40072110, 2025).